CD44 (CD44 molecule (IN blood group))
Diseases named in the same sentence as CD44 in open-access papers (continued):
Sharing a sentence is not in itself a finding about the gene and the disease.
lung carcinoma (continued). "Based on transcript level expression study using quantitative real-time PCR showed five significantly differentially expressed genes SPP1, VEGFA, CD44, FOXO1 and POSTN in EVs cargo derived from lung cancer patients with bone metastasis." (PMID 36424413, 2022). "Analysis of the enriched genes derived from the pathway analysis identified seven genes present in both asthma and lung cancer: BCL3, POSTN, PPARD, STAT1, MYC, CD44, and FOSB." (PMID 35406434, 2022). "In lung cancers, different CSC populations have been identified according to the expression of some markers, such as CD44, CD90, CD117, EGF, Axl, and Sox2, in different combinations." (PMID 36555420, 2022). "The fold changes in gene expression in lung cancer relative to asthmatic cell lines were in line with the in silico prediction for the genes BCL3, CD44, PPARD, POSTN, FOSB, and STAT1." (PMID 35406434, 2022). "The cleavage of the hyaluronan receptor CD44 is mediated by TRAF4 via the activation of RAC1, promoting migration of A549 lung cancer cells." (PMID 33804427, 2021). "Our study aims to deepen the understanding of the role of HA CD44/RHAMM signaling pathway in non-small lung cancer cells and develop emodin as a novel drug for the treatment of lung cancer." (PMID 33407495, 2021). "Functional classification analysis revealed that lung cancer-related genes, such as TOP2A and MKI67, and tumor metastasis-related genes, such as CDH11 and CD44, were significantly up-regulated after 8 weeks of PHMG exposure." (PMID 33737587, 2021). "Next to the formation of spherical cancer organoids, lung cancer stem cells (LCSCs) can be identified using different markers such as cell surface glycoproteins Prominin-1 (CD133) and CD44-antigen (CD44)." (PMID 33925297, 2021). "Meanwhile, at 8 weeks after PHMG exposure, lung cancer-related genes such as TOP2A and MKI67 and tumor metastasis-related genes such as CDH11 and CD44 were significantly upregulated." (PMID 33737587, 2021). "Clinical research demonstrated that the level of CD44+, CD54+, and CD69+ lymphocytes in peripheral blood of lung cancer patients were significantly lower than the health and rose after chemotherapy." (PMID 34633989, 2021). "One of the most commonly used is flow cytometry (FCM) employing CSC-specific cell surface markers, like CD133 and CD44, and the ALDH1A1, which is the most used and described marker for lung cancer stem cells." (PMID 33868998, 2021). "Solid tumor CSCs (CD44+CD24−/lowLineage− cells) have been found in breast, ovarian, prostate, colon, pancreatic, liver, and lung cancers, suggesting that CD34+ and CD44+ are typical CSC markers." (PMID 34671679, 2021). "Our study is the first attempt toward the utility of a double superficial marker such as CD44+/EPCAM+ for the identification and further the targeting of lung cancer stem cells." (PMID 32391123, 2020). "As proof of concept of the ALDH enrichment in the population identified by CD44+/EPCAM+ cells, we performed an additional experiment in which primary lung cancer cells were sorted for CD44/EPCAM antigens." (PMID 32391123, 2020). "In an attempt to achieve dual-target, Huang and coworkers developed CD133 and CD44 aptamer-conjugated nanomicelles loaded with gefitinib (CD133/CD44-NM-Gef) that were capable of simultaneous targeting to CD44+ and CD133+ lung cancer-initiating cells." (PMID 32998391, 2020). "Materials and Methods: This cross-sectional study analyzed the expression of ALDHhigh/low cells and the positivity for CD44 and epithelium cell adhesion molecule (EPCAM) antigens in surgical lung cancer tissues." (PMID 32391123, 2020). "CD44 is closely related to TSG6 as an HA receptor and has been studied as a cancer stem cell marker in lung cancer." (PMID 31548612, 2020). "In lung cancer, the absence of integrin β3 allows OPN-a to stimulate cell growth via the CD44/NFκB pathway, and at high levels of integrin β3 OPN-a inhibits lung cancer cell growth." (PMID 31382483, 2019).
lung carcinoma (continued). "Next, we focused to determine the expression of lung cancer CSC surface markers CD44 and CD133 in these lung cancer cells." (PMID 30816208, 2019). "In contrast to reduced levels of C1NH and CD44 proteins identified here, the levels of these proteins were increased in lung tissues from patients with lepidic predominant invasive adenocarcinoma in previous study, which might be due to the difference in lung cancer types." (PMID 30841875, 2019). "Knockdown of either CD44 or YAP induced cell apoptosis as well as inhibited the cell proliferation, cell cycle progression and migration of lung cancer cells." (PMID 30935014, 2019). "For example, MMP9 enhances CD44 cleavage and shedding, and CD44-mediated cell migration in glioblastoma xenograft cells, while CD44 regulates hyaluronan-dependent MMP2 secretion and tumor invasiveness in human lung carcinoma cells." (PMID 30002682, 2018). "Next, we determined the expressions of CD44 and CD133 (two potential markers for identifying lung cancer stem cells) in H1299 cells by flow cytometry." (PMID 29765324, 2018). "The possible link between CD44 expression by lung cancer cells and chemoresistance was further reinforced by a recent study showing enhanced CD44 and CD133 expression on cisplatin-resistant lung cancer cells." (PMID 30060526, 2018). "We found that CD166 was highly expressed in both normal and lung cancer cells, and we used the combinations of CD166/CD44 and CD166/EpCAM for further analysis." (PMID 25881239, 2015). "To evaluate the stem-like potential of lung cancer oncospheres, we firstly detected the fraction of stem-like surface-marker-positive populations, like CD133+ or CD44+ cells, by flow cytometry." (PMID 25965829, 2015). "For lung cancer stem cell (LCSC) isolation, CD133 and CD44 were widely used as surface markers 14,15." (PMID 25683371, 2015). "Previous studies have demonstrated that COX-2 derived PGE2 activates CD44 and MMP-2, and in turn stimulates invasiveness of lung cancer cells in vitro." (PMID 25190452, 2014). "In archived lung cancer tissues, ALDH markers co-localize more with CD44 in squamous cell carcinoma (n = 5/7) than Adeno Carcinoma (n = 1/12)." (PMID 24019906, 2013). "While the marker profile of lung cancer stem cells remains to be explored, some commonly used strategies that have been used to date include the cell surface stem cell markers, CD133 and CD44, in addition to aldehyde dehydrogenase activity." (PMID 23349823, 2013). "Immunohistochemical analysis of 193 resected lung cancers of mixed histological types showed ALDH was expressed in 82 (42.5%) and CD44 in 119 (61.7%) cases, respectively." (PMID 24091605, 2013). "In clinical lung cancers, recurrence-free survival was longer for patients with low abundance ALDH/CD44-coexpressing cells (p = 0.053)." (PMID 24091605, 2013). "To explore further lung CSC markers, we have screened the expression profile of CD34, CD44, CD133, BMI1 and OCT4 in 10 lung cancer cell lines by flow cytometry." (PMID 21124918, 2010). "The expression profiles of five stem cell markers (CD34, CD44, CD133, BMI1 and OCT4) were screened by flow cytometry in 10 lung cancer cell lines." (PMID 21124918, 2010). "We analyzed the expression profile of putative surface (CD34, CD44, CD133) and nuclear markers (BMI1, OCT4) of stem cells in 10 lung cancer cell lines using flow cytometry." (PMID 21124918, 2010). "Expression of antisense CD44 and treatment of cells with anti-CD44 blocked hyaluronic acid (HA)-dependent MMP-2 secretion and, subsequently, invasion of a human lung carcinoma cell line." (PMID 17343740, 2007).
lung carcinoma (continued). "And there was no acquired high expression of CD146 in another lung cancer brain metastatic cell (H2030-BrM), in which CD44 expression was virtually absent." (PMID 41356185, 2026). "TNFRSF21 (DR6) is a receptor involved in regulating the immune response that contributes to malignant survival, promoting tumor aggressiveness in lung cancer by increasing ERK/FOXM1 signaling, and cancer stem cell characteristics by promoting CD133 and CD44 mRNA expression." (PMID 41440381, 2025). "Using IPA’s Biomarker Filter (Homo sapiens; cancer; lung cancer cell lines), three genes in our panel mapped to established biomarkers (not specifically for MMP12 inhibition): ADAM9 (efficacy/prognosis), CD44 (diagnosis/progression/prognosis), and MMP12 (efficacy)." (PMID 41465234, 2025). "Furthermore, SM-3 treatment led to a significant reduction in the levels of stem cell markers CD133 and CD44, as well as the stem cell transcription factors OCT4 and SOX2, compared to the spheroids treated with Res (50 μM) in lung cancer cells." (PMID 40287470, 2025). "Furthermore, the 3D organoid population treated with SM-3 showed a marked reduction in the levels of stem cell markers (CD44 and CD133) and stem cell transcription factors (SOX2 and OCT4) in lung cancer organoids." (PMID 40287470, 2025). "Additionally, SM-3 treatment resulted in decreased expression of stem cell markers (CD133, CD44, and ALDH1A1) and transcription factors (OCT4, NANOG, and SOX2) in spheroids and organoids from human lung cancer cells by inhibiting the mTOR/pAkt pathway." (PMID 40287470, 2025). "In addition, the high expression of CD44 was capable of inducing ERK phosphorylation, which affects the migratory and invasive potential of lung cancer cells." (PMID 38783892, 2024). "In lung cancer, data on the role of various CD44 SNPs are very limited, while the rs187116 has not been studied at all." (PMID 38067149, 2023). "Additionally, there was a notable reduction in the levels of not only stem cell markers CD133 and CD44, but also the stem cell transcription factor OCT4, compared to spheroids treated with RT (50 nM) in lung cancer." (PMID 38132948, 2023). "Thus, the expression putative surface markers (CD44, CD133) of stem cells were analyzed in lung cancer cell lines using flow cytometry, where we found that the expression of them was reduced in the overexpressed SAV1 cells compared to the control." (PMID 35864957, 2022). "CD44, CD166, and CD55 are known CSC cell surface markers in lung cancer and other cancer types." (PMID 36499099, 2022). "Interestingly, CD44 and FOXO1 transcripts were observed to be down-regulated in primary lung cancer but significantly up-regulated in lung cancer patients with bone metastasis." (PMID 36424413, 2022). "In addition, Notch signaling blockade with shRNA against NOTCH or γ-secretase inhibitors can significantly suppress the growth of CD44+, CD133+, or ALDH+ tumor cells, consistent with a decrease in lung cancer cell growth and chemoresistance." (PMID 35719973, 2022). "Therefore, in the current study, CD44 and SSEA-4 were used as markers for the isolation of MSC cells from the NSC lung cancer and normal lung cells." (PMID 35707369, 2022). "The protein levels of Sp1 and EMT-related markers, including CD44, β-catenin and ALDH1, in 51 lung cancer patients were determined by IHC and grouped them into high and low expression individually, subsequently the relationship between the survival rate and protein levels was studied." (PMID 35034634, 2022). "Additionally, CD44 modulates the expression of transcription factor snail and the mesenchymal phenotype in EGFR Kinase Inhibitors-resistant lung cancer." (PMID 34439211, 2021).
lung carcinoma (continued). "In lung cancer cell lines, down-regulation of NEAT1 could decrease the expression of stemness-related factors, including CD133, CD44, SOX2, OCT4 and NANOG." (PMID 33614649, 2021). "Stem-like cells derived from the A549 lung cancer cell line, positive for CD133, CD56 and CD44 antigen markers, were characterized, intracellular localization of aluminium (III) phthalocyanine chloride tetrasulphonate (AlPcS4Cl) determined and its anti-cancer PDT effects were evaluated." (PMID 34527268, 2021). "In the study of lung cancer, it was found that when ENPP1 gene was knocked out in lung cancer cell lines, the expression of a large number of stem cell markers decreased, including ABCG2, SOX2, NANOG, and CD44." (PMID 33635867, 2021). "We determined the expression level of HAS2, HAS3, CD44, and RHAMM in lung cancer cell lines except for CD44 in H1975 and HAS2 in H460 which might be too low to be detected in our experiment." (PMID 33407495, 2021). "Based on our clinical, in vitro, and in vivo studies, this study provided evidence that CD44 promotes lung cancer metastasis through ERK/ZEB1 activation and may serve as a potential therapeutic target for lung cancer metastasis." (PMID 34439211, 2021). "Immunohistochemical staining of lung cancer tissue specimens revealed that primary tumors with higher CD44 expression showed increased metastasis to regional lymph nodes." (PMID 34439211, 2021). "This similarly applies to lung cancer, where ALDH1 plus several other CSC markers including CD44 and CD133 have been identified as markers for lung CSC, but due to the heterogeneity and plasticity of lung cancer, having a specific marker for lung CSC is difficult." (PMID 32391048, 2020). "Similarly, the lung cancer stem markers ABCG2, CD133, and CD44 were also suppressed by the combination of FO and Se." (PMID 32751169, 2020). "According to the real-time PCR detection results, for the surface marker-related genes of lung cancer stem cells, the expressions of CD13 and CD44 were upregulated in the Apatinib group when compared to the control group, whereas the expressions of ABCG2, CD24, and ICAM-1 were downregulated." (PMID 32849930, 2020). "Subpopulation of nonsmall cell lung cancer (NSCLC) triple-positive for EPCAM, ALCAM, and CD44 possessed CSC characteristics, including being highly proliferative, having greater clonogenicity, ability for self-renewal through spheroid formation, and chemoresistance." (PMID 32085563, 2020). "CD44 and CD133 have been reported as cancer stem cell markers in lung cancer." (PMID 30754694, 2019). "Both of CD44 and CD133 have been reported to be enriched in lung cancer CSCs." (PMID 30816208, 2019). "Lung cancer stem cell markers include the transcription factor SOX2, the metabolic marker aldehyde dehydrogenase isoform 1 (ALDH1), and the cell surface markers CD133, CD44, CD166, and ABCG2." (PMID 29698587, 2018). "CD44 and CD166 were reported to be stem cells surface markers of lung cancer in several researches." (PMID 28076327, 2017). "Among lung cancers, NSCLC tumors express higher levels of CD44 than do SCLC." (PMID 28290155, 2017). "Therefore, we also detected the effects of miR-410 on the expressions of CD44 and CD166 in lung cancer cells." (PMID 28076327, 2017). "Several researchers recently reported CD44 and CD166 were stem cells markers of lung cancer." (PMID 28076327, 2017). "Furthermore, TIC selected by the lung TIC markers ALDH+/CD44+ from HCC827 and the patient-derived lung cancer cell lines, HKUCL2 and HKUCL4, showed higher NFATc2 expression than the ALDH-/CD44- non-TIC counterpart." (PMID 28737489, 2017). "It is difficult to decipher which are the key genes involved in the MET/CD44 axis, but IL-8 has been shown to act as an autocrine growth factor in HNSCC, melanoma, and lung carcinoma and addition of recombinant IL-8 can promote directly the proliferation of HNSCC cell lines." (PMID 26880935, 2016).
lung carcinoma (continued). "Recent studies have demonstrated the importance of this, showing that a combination of CD44v6 and CD44s, but not CD44 alone, is able to predict survival in lung cancer patients, while pancreatic tumors with a “CD44v6+/CD44−” profile are more metastatic." (PMID 27379207, 2016). "CD166+, CD133+, CD44+, and CD24+ITGB4+NOTCHhi cells have been labeled as CSCs or TICs in different studies, but few of these studies could be repeated in lung cancer cell lines or samples." (PMID 25965829, 2015). "Potential markers for identifying lung cancer stem cells include CD133, CD44, ALDH, CD166 and BMI." (PMID 25477004, 2014). "We have analyzed the performance of ALDH/CD44 co-expression as TIC markers and treatment targets of lung cancer using well-validated in vitro and in vivo analyses in multiple established and patient-derived lung cancer cells." (PMID 24091605, 2013). "Another surface marker, CD44, has also been used to isolate CSC from lung cancer." (PMID 23683495, 2013). "To determine if we could identify a relationship between CD44/ALDH expression and histopathological subtypes of lung cancer, tissue sections were evaluated for CD44, ALDH and co expression of CD44 and ALDH." (PMID 24019906, 2013). "We analyzed COR L23, a nonsmall cell lung cancer cell line that was completely negative for both CD44 and CD24 markers." (PMID 22693526, 2012). "CD44 is believed to be a potential marker in lung cancer but not expressed in all lung cancer types." (PMID 22693526, 2012). "Similarly, BCL3, CD44, PPARD, and STAT1 were upregulated in both the mixed group and lung cancer samples; thus, they may also be involved in the transition." (PMID 35406434, 2022). "CD44 is a protein involved in cancer initiation and development and highly affected by RNA splicing, thus we hypothesized that CD44 splicing were regulated by abnormal expression of SFPQ in lung cancer." (PMID 35707369, 2022). "Examination of CD44/PAK1/AKT activation could help to predict response to FGFR1 inhibition, and combination with AKT or PAK1 inhibitors might pave the way toward an effective therapy for FGFR1-dependent lung-cancer patients in cases of resistance to treatment." (PMID 35853934, 2022). "CD44 expression may play a significant role in epidermal growth factor receptor (EGFR)-mutant neoplasms, particularly in early NSCLC, and CD44 is important in predicting EMT upon EGFR-TKI monotherapy in patients with lung cancer." (PMID 35719973, 2022). "For example, CD133 and CD44 aptamer-conjugated dual-targeted nanomicelles loaded with gefitinib, an epidermal growth factor receptor (EGFR) inhibitor, more effectively eradicated CD133/CD44 double-positive lung cancer-initiating cells compared with the single-targeted or non-targeted nanomicelles." (PMID 34064635, 2021). "Previously, various CSC markers and self-renewal proteins such as CD133, CD44, ALDH1, ESA, β-Catenin, and SHH were found to be overexpressed in various cancers, including, but not limited to, pancreatic, head and neck cancer, prostate, breast, ovary, and lung cancer." (PMID 28122356, 2017). "In a rat model of orthotopic lung cancer, intranasal administration of liposomal triptolide significantly inhibited lung tumor growth and these effects were paralleled by reduced tumor cell proliferation, and lower HAS, HA and CD44/RHAMM levels in the tumor tissues." (PMID 28460475, 2017). "Therefore, in A549 and H1299 lung cancer cell lines, CD44 does not appear to represent a specific population of cells." (PMID 24160469, 2013). "However, the mRNA relative levels of Bmi1, CD133 and CD44 by RT-PCR were not significantly different between lung cancer and non-malignant lung tissues analyzed by Mann–Whitney U test, nor were the expression rates of CD44 and Msi2." (PMID 23683495, 2013).